POLG-DT (POLG divergent transcript)
Gene: Long non-coding RNA gene on chromosome 15 (89,334,583 to 89,336,161, forward strand). Ensembl gene ENSG00000261441.
Gene Ontology:
Molecular function: triplet codon-amino acid adaptor activity
Biological process: translation